CBARP (CACN subunit beta associated regulatory protein)
Description:
Negatively regulates voltage-gated calcium channels by preventing the interaction between their alpha and beta subunits. Thereby, negatively regulates calcium channels activity at the plasma membrane and indirectly inhibits calcium-regulated exocytosis.
Synonyms: C19orf26; MGC40084; DOS; BARP
Tractability: Antibody: UniProt places it where antibodies can reach, with medium confidence; UniProt predicts a signal peptide or a membrane-spanning region; its Gene Ontology location is reachable by antibodies, with medium confidence. PROTAC: its protein half-life has been measured.
Gene: Protein-coding gene on chromosome 19 (1,228,284 to 1,239,465, reverse strand). Ensembl gene ENSG00000099625.
Subcellular location: Cytoplasmic vesicle, secretory vesicle, synaptic vesicle membrane; Cell membrane; Cell projection, growth cone
Subcellular location (Human Protein Atlas): Nucleoplasm
Gene Ontology:
Molecular function: protein binding; transmembrane transporter binding
Biological process: negative regulation of calcium ion transmembrane transport; negative regulation of calcium ion-dependent exocytosis; negative regulation of voltage-gated calcium channel activity
Cellular component: growth cone; plasma membrane; secretory granule; synaptic vesicle membrane
Genetic constraint (gnomAD): Loss-of-function variants: 23 observed, 29.44 expected, observed/expected ratio (o/e) 0.78, 90% interval 0.56 to 1.11. The synonymous counts are far from expectation, so gnomAD's model fits this gene poorly and the ratio says little. Missense variants: 607 observed, 484.36 expected, observed/expected ratio (o/e) 1.25, 90% interval 1.17 to 1.34. Synonymous variants: 293 observed, 214.7 expected, observed/expected ratio (o/e) 1.36, 90% interval 1.24 to 1.5.
Homologues: Orthologues: macaque CBARP (97% identical), pig CBARP (83% identical), mouse Cbarp (83% identical), rat Cbarp (83% identical), guinea pig CBARP (81% identical), dog CBARP (78% identical), chimpanzee CBARP (52% identical), tropical clawed frog cbarp (44% identical), zebrafish cbarpb (41% identical).
Diseases named in the same sentence as CBARP in open-access papers:
CBARP is named in the same sentence as 5 diseases in open-access papers, as found by Europe PMC text mining. Sharing a sentence is not in itself a finding about the gene and the disease.
CBARP shares sentences with these, for which no sentence is quoted: Anxiety (1 paper); cancer (1); psychiatric disorder (1); psychiatric disturbance (1); schizophrenia (1).